MIR630 (microRNA 630)
Synonyms: hsa-mir-630; MIRN630
Gene: MicroRNA gene on chromosome 15 (72,587,217 to 72,587,313, forward strand). Ensembl gene ENSG00000283798.
Diseases named in the same sentence as MIR630 in open-access papers:
MIR630 is named in the same sentence as 2 diseases in open-access papers, as found by Europe PMC text mining. Sharing a sentence is not in itself a finding about the gene and the disease. The quoted sentences say what the papers report.
embryonal carcinoma (1 paper, 2021). A non-seminomatous malignant germ cell tumor characterized by the presence of large germ cells with abundant cytoplasm resembling epithelial cells, geographic necrosis, high mitotic activity, and pseudoglandular and pseudopapillary structures formation. "Since high NANOG expression is associated with poor differentiation of solid tumors, it was interesting to know whether MIR630 promotes the differentiation of embryonal carcinoma cells." (PMID 35008480, 2021).
gastric cancer (1 paper, 2026). A primary or metastatic malignant neoplasm involving the stomach. "The two loci (DOCK10 and FCN1-FCN2) replicated from CoGaPro1, and the 11 loci replicated from CoGaPro2 (CDK15, CROCC2-SNED1, TLR2-RNF175-SFRP2, WWC2, RELN, ZMYM5-ZMYM2, KLF12, SKAP1, CABLES2, and MIR630) gave further support for these genes being associated with a risk of CRC and gastric cancer." (PMID 41516419, 2026).